CD55 (CD55 molecule (Cromer blood group))
Diseases named in the same sentence as CD55 in open-access papers (continued):
Sharing a sentence is not in itself a finding about the gene and the disease.
myasthenia gravis (3 papers, 2016 to 2023). Myasthenia gravis (MG) is a rare, clinically heterogeneous, autoimmune disorder of the neuromuscular junction characterized by fatigable weakness of voluntary muscles. "In the actively immunized experimental autoimmune myasthenia gravis mice deficient in either CD55 or CD59, a significant increase in complement deposition at the end-plates was observed and worsened disease outcome associated with increased levels of serum cytokines was observed." (PMID 27056040, 2016). "Firstly, the fusion protein designed to treat myasthenia gravis contains CD55 and an antibody fragment." (PMID 33362763, 2020).
neuroblastoma (3 papers, 2016 to 2024). Neuroblastoma (NB) is the most common solid, extracranial childhood tumor. "Indeed, high CD55 expression in a neuroblastoma is associated with increased sphere-forming efficiency and self-renewal capacity, as well as poor survival outcomes in patients." (PMID 38612911, 2024). "In our study we revealed that CD55 is a novel target of hypoxia-inducible factor HIF-2α in neuroblastoma (NB) cells." (PMID 27043658, 2016). "In addition, CD55 has a non-canonical function as a CSC-associated factor and marker, promoting cancer progression and chemoresistance in cervical, ovarian, neuroblastoma, breast, and endometrial cancer." (PMID 38612911, 2024).
non-Hodgkin lymphoma (3 papers, 2014 to 2026). Distinct from Hodgkin lymphoma both morphologically and biologically, non-Hodgkin lymphoma (NHL) is characterized by the absence of Reed-Sternberg cells, can occur at any age, and usually presents as a localized or generalized lymphadenopathy associated with fever and weight loss. "Similar findings were reported in an earlier study where lymphoid cells especially non-Hodgkin’s lymphoma cells, were reported to lack CD55, although, in most cases, another phosphatidyl inositol-anchored protein, CD59, was still present." (PMID 41526546, 2026). "Similarly, the use of mAbs blocking CD55 and CD59 in addition to Rituximab treatment leads to increased tumor toxicity in non-Hodgkin’s lymphoma." (PMID 33614473, 2020).
osteoarthritis (3 papers, 2012 to 2023). A noninflammatory degenerative joint disease occurring chiefly in older persons, characterized by degeneration of the articular cartilage, hypertrophy of bone at the margins and changes in the synovial membrane. "In conclusion, our study sheds light on the potential significance of CD39+CD55− synovial fibroblasts in osteoarthritis, their myofibroblast-like phenotype, and their association with joint pain." (PMID 38002046, 2023). "Our study sheds light on the potential significance of CD39+CD55− synovial fibroblasts in osteoarthritis, their myofibroblast-like phenotype, and their association with joint pain." (PMID 38002046, 2023). "The proportion of Fb subsets (CD39+CD55− and CD39−CD55+) and their association with osteoarthritis pathology were evaluated." (PMID 38002046, 2023). "Analysis of MSCs positive for CD55 will therefore provide a better clarification of the pathology of osteoarthritis." (PMID 29720268, 2018). "We selected CD55, a complement inhibitor, as a specific marker for the surface region because activation of complement in the synovial membrane plays an important role in the pathogenesis of osteoarthritis." (PMID 29720268, 2018). "Second, we selected CD55+ as the marker for synovial cells from the surface region, but because we investigated synovium derived from osteoarthritis patients, these cells may be representative of the inflammatory condition." (PMID 29720268, 2018).
peritonitis (3 papers, 2011 to 2023). Inflammation of the peritoneum (tissue that lines the abdominal wall and covers most of the organs in the abdomen). "Peritoneal biopsies were additionally evaluated for CD46, CD55, and CD59 expression depending on their history of PD-associated peritonitis." (PMID 28542228, 2017). "To further substantiate the point that migration of Cd55-/- granulocytes to sites of inflammation is normal, we induced sterile peritonitis with 4% thioglycollate in wild-type and Cd55-/- mice." (PMID 21984892, 2011). "In peritoneal biopsy tissues obtained at PD catheter removal, we investigated the severity of peritonitis-associated peritoneal injuries and the expression of CRegs, CD46, CD55, and CD59 against peritoneal tissues without any episode of peritonitis." (PMID 37298097, 2023). "CD55 expression is decreased in patients with fast transporter membrane function, whereas peritonitis and PD duration do not appear to alter CReg expression." (PMID 28542228, 2017).
synovitis (3 papers, 2016 to 2017). Inflammation of a synovial membrane. "Then, for in-depth analysis of the main synovial cell populations present in the synovial tissue, we analyzed CD68 and CD55 to establish the percentage of synovial macrophages and synovial fibroblasts, in both low- and moderate-grade synovitis." (PMID 27044395, 2016). "The CD55 typical marker of synovial fibroblast was positive both on the sublining and lining layers and was approximately 70 % positive in both low- and moderate-grade synovitis." (PMID 27044395, 2016).
ulcerative colitis (3 papers, 2022 to 2026). An inflammatory bowel disease involving the mucosal surface of the large intestine and rectum. "An analytical study on bioinformatics suggested that CD55 may act as a potential molecule for a tissue biopsy in ulcerative colitis (UC)." (PMID 38660311, 2024). "Furthermore, immunohistochemical examination have revealed that the expression of CD55 was weak in non-active lesions of UC patients, but significantly enhanced in the inflamed mucosa of patients with active ulcerative colitis." (PMID 38660311, 2024).
acute leukemia (2 papers, 2025 to 2026). A clonal (malignant) hematopoietic disorder with an acute onset, affecting the bone marrow and the peripheral blood. "In order to determine the effect of post transcriptional knockdown of CD46 and CD55 on cell viability in acute leukemia, MTT assay was performed where the absorbance of the formazan product was measured at 595 nm." (PMID 41526546, 2026). "This study highlights the role of complement regulatory proteins; CD46 and CD55 in the pathogenesis of acute leukemia through their contribution to immune evasion and their ability to exhibit protection of leukemic cells against complement-dependent cytotoxicity." (PMID 41526546, 2026).
adenoma (2 papers, 1992 to 2025). A neoplasm arising from the epithelium. "In light of the preclinical findings identifying a role for stromal remodelling and wnt ligand dependency we assessed some very small human HMPS, TSA and conventional adenoma lesions to look for evidence of de-repressed CD55(+) Wnt2b(+) fibroblast cells." (PMID 40467544, 2025). "Although the mode of DAF(CD55) expression is not correlated with tumour prognostic parameters, the upregulation of DAF(CD55) in a subset of adenomas and carcinomas needs further investigation concerning protection of tumour cells against complement cytotoxicity." (PMID 1384641, 1992). "However, 5/20 adenomas expressed DAF(CD55) on the cell surface of all tumour cells, 5/20 adenomas were completely negative, 10/20 adenomas expressed DAF(CD55) in various amounts." (PMID 1384641, 1992).
allergic respiratory disease (2 papers, 2018 to 2020). A respiratory system disease with a basis in a pathological type I hypersensitivity reaction. "A CD55 SNP linked to decreased transcriptional activity, was associated with susceptibility to pollen and mite-induced respiratory allergies and enhanced specific IgE responses." (PMID 33362763, 2020).
colon adenocarcinoma (2 papers, 2019 to 2020). "Immunohistochemical analysis revealed the expression of CD59, CD55, and CD46 on uveal melanoma, thyroid carcinoma, lung and kidney cancer, colon adenocarcinoma, and prostate cancer." (PMID 31024572, 2019). "For example, TNFα and IL-1ß enhanced the expression of CD55 and CD59 in colon adenocarcinoma cells." (PMID 31024572, 2019). "Additionally, CD55 has positive correlation with few immune cell infiltration levels in colon adenocarcinoma (COAD), but its correlation with immune marker sets was not statistically significant." (PMID 33614473, 2020).
complement deficiencies (2 papers, 2023 to 2025). "Considering that complement deficiency improves cutaneous wound healing, in our model system, lower Cd55 expression might facilitate complement activation and, thereby, delay wound healing." (PMID 36835537, 2023). "Although complement deficiencies are generally associated with a low prevalence of autoimmune and autoinflammatory manifestations compared with other IEI groups, CD55 deficiency stands out for its high autoinflammatory burden." (PMID 41394846, 2025).
diabetic retinopathy (2 papers, 2013 to 2019). "Recent studies have described elevated levels of membrane attack complex (MAC) and reduced levels of membrane associated complement regulators including CD55 and CD59 in the retina of diabetic retinopathy patients as well as in animal models of this disease." (PMID 24167638, 2013).
E. coli infection (2 papers, 2018 to 2026). "The ESR can regulate the expression of CD55 and thus affect the colonization of E. coli, and when activated, it can protect against the inflammation of bladder epithelial cells caused by E. coli infection by downregulating CD55 expression." (PMID 41563994, 2026).
endometrioid ovarian cancer (2 papers, 2017 to 2025). "We next investigated the utility of CD55 in predicting outcomes of patients with endometrioid ovarian cancer by using the Kaplan-Meier plotter biomarker assessment database." (PMID 28838952, 2017).
glomerular sclerosis (2 papers, 2014 to 2023). Accumulation of scar tissue within the glomerulus. "Recent findings suggested that regulation of C3 convertase in podocytes by CD55, a decay-accelerating factor, is implicated in determining proteinuria and glomerular sclerosis in mice models of glomerulosclerosis induced by adriamycin." (PMID 37503337, 2023).
head and neck squamous cell carcinoma (2 papers, 2021 to 2025). A squamous cell carcinoma that arises from any of the following anatomic sites: lip and oral cavity, nasal cavity, paranasal sinuses, pharynx, larynx, and salivary glands. "For example, head and neck squamous cell carcinoma (HNSCC) cells express significantly elevated levels of CD46, CD55 and CD59, when compared to benign keratinocyte cells." (PMID 33802004, 2021).
immunodeficiencies (2 papers, 2023 to 2024). "Based on our experience, FCM provided direct diagnostic insights for immunodeficiencies such as SCID, OS, MHC-II deficiency, WAS, XLA, XL-CGD, FHL, LAD-1, AR-CD46 deficiency, and CD55 deficiency." (PMID 39072316, 2024).
Insulin resistance (2 papers, 2017 to 2024). Increased resistance towards insulin, that is, diminished effectiveness of insulin in reducing blood glucose levels. "GTT analysis demonstrated that mice that received CD55+ hiGC transplantation showed significant rescue of insulin resistance." (PMID 38192172, 2024).
insulin-dependent diabetes (2 papers, 2006 to 2010). "Indeed, the expression of complement receptor 3 on monocytes from non-insulin-dependent diabetes patients was strongly decreased and the CD55 and CD59 complement regulatory protein-positive monocytes were lower in type 2 diabetic patients." (PMID 20877467, 2010).
lung adenocarcinoma (2 papers, 2012 to 2019). A carcinoma that arises from the lung and is characterized by the presence of malignant glandular epithelial cells. "Furthermore, examination of data in the Cancer Genome Atlas (TCGA) reveals gene amplification or increased expression of the complement regulatory proteins, CD46 and CD55, in approximately 25% of human lung adenocarcinomas." (PMID 31134065, 2019). "Furthermore, examination of data in the Cancer Genome Atlas (TCGA) reveals gene amplification or increased expression of complement regulatory proteins, CD46 and CD55 in ~25% of human lung adenocarcinomas." (PMID 31134065, 2019).
mucinous adenocarcinoma (2 papers, 1992 to 2022). An invasive adenocarcinoma composed of malignant glandular cells which contain intracytoplasmic mucin. "Additionally, the average level of CD55 in mucinous adenocarcinoma tissue is significantly higher than that in adenocarcinoma tissue (–E)." (PMID 36741376, 2022).
multiple sclerosis (2 papers, 2021 to 2024). A progressive autoimmune disorder affecting the central nervous system resulting in demyelination. "The binding of CD55 to CD97 can protect several cell types from complement-mediated damage, and the CD55–CD97 interactions are involved in the pathogenesis for multiple sclerosis, synovial inflammation, and rheumatoid arthritis." (PMID 33992645, 2021).
Obesity (2 papers, 2021 to 2024). Accumulation of substantial excess body fat. "Overweight or obesity is positively correlated with cardiovascular events and FI or CD55,56." (PMID 38783080, 2024). "Similarly, human hepatocytes are characterized by high expression of a battery of complement inhibitors, including CD46, CD55, CD59, and factor H, although it is not known whether their expression is stable in metabolic disorders such as obesity or cachexia." (PMID 34830921, 2021).
Pleural effusion (2 papers, 2018 to 2023). The presence of an excessive amount of fluid in the pleural cavity. "The specificity of the Ab1 anti-CD55 monoclonal antibody was confirmed by flow cytometry analysis of CD55-positive H460 cells (NSCLC derived from pleural effusions) and CD55-negative H69 cells (small cell lung carcinoma)." (PMID 29895866, 2018). "The expression levels of soluble CD46 (sCD46), soluble CD55 (sCD55), and soluble CD59 (sCD59) in pleural effusion were quantified by enzyme-linked immunosorbent assay, and the receiver operating characteristic (ROC) curves were plotted to evaluate the diagnostic and co-diagnostic values." (PMID 36820087, 2023).
pneumonia (2 papers, 2011 to 2024). An acute, acute and chronic, or chronic inflammation focally or diffusely affecting the lung parenchyma, caused by an infection in one or both of the lungs (by bacteria, viruses, fungi, or mycoplasma.). "We concluded that a better protection from bacteremia due to increased granulocyte numbers rather than qualitative improvement of immunity in the lungs likely reduced lethality from S. pneumonia in Cd55-/- mice." (PMID 21984892, 2011). "Furthermore, mice lacking CD55 were better protected against S. pneumoniae-induced pneumonia." (PMID 21984892, 2011).
relapsing fever (2 papers, 2022 to 2025). Relapsing fever is an infection caused by bacteria of the genus Borrelia, excluding those responsible for Lyme disease belonging to the Borrelia burgdorferi complex. "Expanding the use of BASEHIT, CD55 was identified to bind Borrelia crocidurae and Borrelia persica, two pathogens causing relapsing fever." (PMID 40392222, 2025). "Analysis of the results revealed that human CD55 bound to B. crocidurae and Borrelia persica, two spirochetes that cause relapsing fever, and exceeded a stringent significance threshold." (PMID 36036625, 2022). "In summary, our results indicate that CD55 is a host factor that is manipulated by the causative agents of relapsing fever for immune evasion." (PMID 36036625, 2022). "Through targeted screening of relapsing fever-causing spirochetes, we determined that CD55, a complement regulator, interacts with B. crocidurae, allowing us to validate its role in erythrocyte aggregation and pathogenesis." (PMID 36036625, 2022). "In this study, we identified CD55 as a novel host interaction partner with B. crocidurae and B. persica, two etiologic agents of relapsing fever." (PMID 36036625, 2022). "At present, there is little information about the pathogenesis of B. persica, and further studies will delineate the role of CD55 in B. persica infection and that of other relapsing fever strains, including but not limited to emerging pathogens like B. miyamotoi." (PMID 36036625, 2022).
schizophrenia (2 papers, 2017 to 2020). A major psychotic disorder characterized by abnormalities in the perception or expression of reality. "CD55 mRNA was not significantly correlated with any complement transcripts in any group, except for a trend toward a positive correlation with GFAP mRNA in schizophrenia (r = 0.36, p = 0.065)." (PMID 33133060, 2020).
uterine serous carcinoma (2 papers, 2015 to 2024). "The study found that uterine serous carcinoma is characterized by high levels of mCRPs CD46, CD55, and CD59." (PMID 39337406, 2024). "Consistent with this view, recent data from our group in uterine serous carcinomas, a subset of biologically aggressive tumors histologically similar to CS, demonstrate overexpression of mCRPs CD46, CD55 and CD59 in the majority of the tumors." (PMID 26474755, 2015).
vivax malaria (2 papers, 2018 to 2019). "Further, the level of CD55 and CD59 on reticulocytes was positively associated with haemoglobin level for falciparum and vivax malaria, respectively (CD55: R = 0.53, p = 0.053; CD59: R = 0.55, p = 0.027)." (PMID 31533836, 2019). "Expression of CR1, CD55, CD59, and CD47 was also assessed on reticulocytes during falciparum and vivax malaria and healthy controls." (PMID 31533836, 2019).
abortion (1 paper, 2019). the ending of pregnancy by removing a fetus or embryo before it can survive outside the uterus. "Interestingly, increased complement activation has been recorded in human placentas following spontaneous abortion, while CD46 and CD55 (complement regulators) became reduced." (PMID 31395028, 2019).
acute pancreatitis (1 paper, 2017). An acute inflammatory process that leads to necrosis of the pancreatic parenchyma. "IL-4 reduced necrosis in this model of acute pancreatitis and authors suggested that this effect was related to enhanced expression of complement regulatory proteins, CD55 and CD59." (PMID 28665321, 2017).
Allergy (1 paper, 2022). An allergy is an immune response or reaction to substances that are usually not harmful. "This protein group includes proteins involved in cell stress response (HSPB1), mucosal protection and allergy (MUC1), complement activation (CD55) and actin polymerization (CAPG, APRT, TPPP3)." (PMID 35590254, 2022).
B-cell lymphoma (1 paper, 2020). "While the KSHV-negative B-cell lymphoma cell line, BJAB, expressed CD55 and CD59, both the KSHV-infected PEL cell lines, BCBL-1 and BCP-1, did not express CD55 or CD59." (PMID 32260199, 2020).
bacteremia (1 paper, 2011). "Concomitant with the increase in blood granulocyte numbers, Cd55-/- mice challenged with the respiratory pathogen Streptococcus pneumoniae developed less bacteremia and died later after infection." (PMID 21984892, 2011).
bone marrow failure syndrome (1 paper, 2021). "Occasionally, CD55 and/or CD59 deficient clones are detected in non-cytopenic patients and patients with no apparent bone marrow failure syndromes and in about 4,1% in healthy volunteers (1.6, 0.8% and 1,6% with CD55−/CD59-, CD55−/CD59+, and CD55+/CD59- cells respectively)." (PMID 33691713, 2021).
bronchioloalveolar carcinoma (1 paper, 2018). A well or moderately differentiated morphologic variant of lung adenocarcinoma characterized by tumor growth along the alveolar structures without stromal, vascular, or pleural invasion. "Additionally, 177Lu-anti-CD55 inhibited the survival of H358 cells (bronchioloalveolar carcinoma cells, a subtype of NSCLC), while unlabeled CD55-specific antibodies did not reduce viability." (PMID 29895866, 2018).
Budd-Chiari syndrome (1 paper, 2025). "Flow cytometry using FLAER (Fluorescent AERolysin) and CD55/CD59 confirmed large PNH clones in granulocytes and monocytes, consistent with classic PNH complicated by hepatic vein thrombosis, Budd-Chiari syndrome (BCS)." (PMID 41450399, 2025).